TLR4 (toll like receptor 4)
Diseases named in the same sentence as TLR4 in open-access papers (continued):
Sharing a sentence is not in itself a finding about the gene and the disease.
ischemia (continued). "In a model of focal cerebral ischemia, iNOS was reduced in Tlr4−/− mice 24 h after ischemia." (PMID 28912751, 2017). "Both HMGB1 and TLR4 promote skeletal muscle recovery after ischemia." (PMID 26744383, 2016). "However, it is thought that transient ischemia-induced activation of NF-κB/p65 via toll like receptor 4 or 2 in glial cells would exert secondary injury to neurons by producing neuro-toxic cytokins such as TNFα and IL-1β." (PMID 24800741, 2014). "Since dexmedetomidine hydrochloride was observed to mediate a protective effect against lung injury following intestinal ischemia-reperfusion, molecules upstream of the cytokines were analyzed, including the TLR4/MyD88 pathway which mediates cytokine production." (PMID 24255662, 2013). "An interesting additional finding from our study is that there is significantly increased MCP1/CCL2 expression and MPO activity in the right lung following left lung ischemia-reperfusion and that this right lung response is attenuated in Myd88-/- and, to a lesser extent Tlr4-/- mice." (PMID 24146959, 2013). "Compared with the ischemia control group, the neurobehavioral scores, the infarction volumes, the apoptotic cells, the expressions and concentrations in brain tissue of TLR4, NFκB and TNFα were obviously decreased both in the picroside 2 and salvianic acid A sodium groups (P < 0.01)." (PMID 20618938, 2010). "Furthermore, loss of MD1 was associated with several cardiovascular diseases; it aggravates maladaptive left atrial fibrosis, ischemia/reperfusion injury, ischemia/reperfusion-related arrhythmia, and inflammation through enhanced activation of the TLR4 signaling pathway." (PMID 36136452, 2022). "Moreover, our results show now that TLR4 blockade with TAK-246 greatly reduces cell viability and phosphorylation of Akt and ERK1/2 during the treatments of simulated ischemia only and sI/R only, suggesting that TLR4 activation exerts a protective role in CFs during these adverse conditions." (PMID 34169098, 2021). "Thus, sporadic WMH could be a result of the actions of LPS-TLR4 mediated injury and/or Aβ-TLR4 mediated injury to myelin possibly in combination with ischemia/hypoxia." (PMID 29520228, 2018). "Indeed, ischemia-exposed antigens on the membrane could bind with the toll-like receptor 4 (TLR4) during reperfusion and activate the related immune response." (PMID 27145782, 2016). "As RP105 inhibits TLR4 signaling, we hypothesized that RP105 deficiency would lead to an unrestrained TLR4-mediated inflammatory response and hence to enhanced blood flow recovery after ischemia." (PMID 24945347, 2014). "In investigations regarding hepatic ischemia—reperfusion injury, Eritoran, a crucial TLR4 antagonist, mitigates liver inflammation and cellular impairment through the blockade of the HMGB1—TLR4 axis." (PMID 40877572, 2025). "The results suggest that WEU inhibits the activation of the TLR4/p38 MAPK and NF-κB signaling pathways, attenuating neuroinflammation induced by ischemia." (PMID 40004043, 2025). "TLR4−/− mice and mice given LPS-RS, a TLR4 antagonist, exhibited decreased systemic IL6 and TNF-α levels after hindlimb ischemia, implicating the role of TLR4 in ischemia-induced systemic inflammatory cytokine production." (PMID 38510939, 2024). "At the same time, L‐F001 can inhibit the activation of TLR4/MyD88 pathway in neonatal rat HIBD model, indicating that L‐F001 plays a neuroprotective role after hypoxic‐ischemia by regulating inflammatory response through the TLR4/MyD88 pathway." (PMID 37822185, 2023). "Prior investigations revealed that TLR4, HMGB1 and NF‐κB are essential proinflammatory modulators of ischemia‐induced brain injury." (PMID 37132060, 2023). "Ischaemia increases caspase-3 reactivity in the ganglion cell layer (GCL) of mouse retina, which was mainly induced via TLR4-mediated proinflammatory cytokines." (PMID 38983565, 2022).
ischemia (continued). "In vivo, the expression of the TLR4/MyD88/NF-κB pathway was upregulated in the WT ischemia group and downregulated in the PCSK9−/− ischemia group." (PMID 35832650, 2022). "Further studies are needed to determine the role of TLR4 signaling in penumbral astrocytes during chronic focal ischemia and the role of HMGB1-TLR4 signaling in activation of A1 vs A2 reactive astrocytes." (PMID 32148958, 2020). "This led to a greater increase in TLR4, P2X7, IκBα activation, NLRP3, ASC, cleaved caspase-1, and pro-inflammatory cytokine IL-1β levels in the Stress+ISCH group compared to the ischemia-alone group." (PMID 32466385, 2020). "HMGB1, an endogenous ligand of TLR4, can drive the pathogenesis of inflammatory and angiogenic diseases and immune regulation, such as CNV, ischemia-reperfusion injury and hemorrhagic shock, though HMGB1/TLR4 signaling pathway." (PMID 32023953, 2020). "Tanshinone II A (Tan IIA) markedly reduced the expression levels of HMGB1, TLR4, RAGE, and NF-κB after ischemia in rats." (PMID 28127491, 2017). "HO-1 activator CoPP can reduce the expressions of TLR2, TLR4, IRAK-4 and TRAF6, and markedly increases the expressions of TLR negative regulators, such as SOCS-1, IRAK-M and SHIP-1, in ischemia/reperfusion liver injury in rat." (PMID 29057806, 2017). "There was a significant positive correlation between TLR2, TLR4, IRAK3 and IRAK4 expression and the degree of ischemia as assessed by serum lactate levels and the time until return of spontaneous circulation." (PMID 27260481, 2016). "Toll-like receptor 4 (TLR4) is important for the pathogenesis of inflammatory reactions and the promotion of pain processing after ischemia/reperfusion (IR) in spinal cord." (PMID 27760212, 2016). "Our data reveals that treatment with IVIg significantly prevented ischemia-induced increased neuronal expressions of TLR2, TLR4 and TLR8." (PMID 25886362, 2015). "Our data has shown that IVIg not only prevented ischemia-induced increased expression levels of TLR2, TLR4 and TLR8 and attenuated its signalling cascades but also ischemia-induced cleavage of apoptotic protease caspase-3." (PMID 25886362, 2015). "Similarly, the degeneration of retinal ganglion cells (RGCs) induced by ischemia and axotomy could be reduced in TLR4-knockout mice, and the phosphorylation levels of ERK-1/-2, c-Jun N-terminal kinase (JNK)-1/-1, and p38 were significantly decreased, with a low level of inducible NO synthase." (PMID 25928750, 2015). "The protective mechanism of ischemic postconditioning was investigated by comparing its effects on apoptosis, production of the neurotoxic cytokine IL-1β and the transcription and expression of TLR2, TLR4 and IRAK4 in the 2 and 4.5 hour ischemia groups." (PMID 24460643, 2014). "The elevated expression of TLR4, TLR2, MyD88 and NF-κB is thought to be consistent with ischemia-evoked neuron injury and death through an inflammatory mechanism." (PMID 23434667, 2013). "Moreover, toll-like receptor 4 (TLR4), an upstream regulator of inflammation and apoptosis, was upregulated in the ischemia and I+R groups, reflecting heightened inflammatory signaling." (PMID 40001595, 2025). "They found that inhibition of TLR4 by its specific inhibitor TAK-242 in a mouse model of hindlimb ischemia did not negatively influence perfusion recovery after ischemia, despite its potential inhibitory effects on angiogenesis." (PMID 38510939, 2024). "Additionally, studies have elucidated that PAD4, P38 and ERK can activate various inflammatory pathways, including microglia, TLR4, NF‐κB and NLRP3 pathways, culminating in an inflammatory cytokine storm that exacerbates ischemia‐induced cerebral injury." (PMID 39099086, 2024). "Myotubes from patients with CLTI expressed greater levels of TLR4 as compared with those from patients with no PAD after exposure to the simulated ischemia." (PMID 38510939, 2024).
ischemia (continued). "Moreover, in cardiomyocytes, CD180 was able to effectively reduce TLR4-mediated production of pro-inflammatory IL-6 and TNF-α in response to ischemia." (PMID 37460961, 2023). "The NF‐κB p65, TLR4 and HMGB1 protein contents were markedly enhanced following ischemia." (PMID 37132060, 2023). "Moreover, genetic deletion or pharmacological inhibition of S100A8/A9 can inhibit the TLR4/NLRP3/IL-1β pathway, suppressing ischemia-induced granulopoiesis and improving cardiac dysfunction." (PMID 36768433, 2023). "We next assessed modulation of plasma levels of miR-329-5p, identified by reverse target prediction analysis based on its potential to regulate inflammatory and immune mediators (e.g., TLR-4, IL-1 and TNF-related signaling pathways) involved in ischemia and PC." (PMID 35359933, 2022). "In this study, TLR4 was mainly upregulated in the CA3 region of hyperglycemic rats with ischemia-induced seizures, and this finding was not correlated with ischemic cell death." (PMID 36619717, 2022). "Finally, to verify that the activation of microglia and astrocytes were initiated by TLR4 and NF-κB respectively, we investigated the colocalization of GFAP and P-NF-κB and the colocalization of Iba1 and TLR4 in the ischemia penumbra." (PMID 32917229, 2020). "It is important to note that we did not observe TLR4 protein staining in the contralateral nonischemic hemispheres in our acute and chronic ischemia models." (PMID 32148958, 2020). "Besides, it has been suggested that myocardial TLR4 mediates cardiac chemokine response through a mechanisms involving HSC70, released during ischemia." (PMID 25566092, 2014). "When ischemic postconditioning was administered, TLR2 or TLR4 positive staining cells reduced markedly in the 2 hour ischemia group, but not in the 4.5 hour ischemia group." (PMID 24460643, 2014). "This is consistent with studies finding that mice lacking TLR4 are protected against brain insults including models of ischemia, trauma, genetic neurodegeneration and epilepsy as well as alcohol and toxin induced neuropathology." (PMID 24551070, 2014). "In summary, our study demonstrates that exposure to PCB153 bound onto silica nanoparticles triggers TLR4/TRAF6-regulated inflammatory responses and alterations of TJ protein expression, which then contribute to enhanced brain injury following ischemia/reperfusion." (PMID 23690990, 2013). "By contrast, some ligands of TLR4 or TLR2 could be used as preconditioning inducer, which would enhance cerebral resistance to severe ischemia and reperfusion." (PMID 23864765, 2013). "There are many studies on the effects of TLR4 in nonbiological inflammatory injuries (e.g., ischemia of the myocardium, liver, and brain), but there are few reports on ischemic nonbiological infective injury." (PMID 20182634, 2009). "Also with regard to hepatic ischemia/reperfusion injury, it has been demonstrated that inhibition of the intrinsic pathway of apoptosis and autophagy was mediated partly through downregulation of HMGB1/TLR4/NF-κB axis." (PMID 29420582, 2018). "Also, lack of CD180, a specific inhibitor of the TLR4-mediated inflammatory response, accelerated inflammation and retarded blood flow recovery after ischemia." (PMID 30460242, 2018). "In one hand, myocardial cell necrosis triggered during ischemia results in the release of necrotic products and cellular constituents such as heat shock proteins (HSP) and nuclear DNA-binding protein high mobility group box (HMGB-1) capable of activating the TLR2 and TLR4 signaling." (PMID 25566092, 2014). "Isoliquiritigenin decreased, among other targets, the gene expression of TLR4 in RAW 264.7 macrophage line, and luteolin administrated at different doses to rats was able to suppress the overexpression of TLR4 and TLR5 induced by ischemia in the cerebral cortex at both protein and gene level." (PMID 26785232, 2014).
ischemia (continued). "Our previous study showed that only the MyD88 but not the TRIF pathway was involved in TLR4-mediated ischemia damage, suggesting that although TLR4 participates in both ischemia- and hemorrhage-induced brain injury, the underlying signaling pathway is different." (PMID 22394415, 2012). "Furthermore, the TLR4/MyD88/MAPK signaling pathway was observed to be involved in the mechanism of the protective effect of dexmedetomidine on the lung following I/R injury, although an α2-adrenergic antagonist failed to neutralize the effect of dexmedetomidine on acute ischemia-induced lung injury." (PMID 24345905, 2014).
melanoma (146 papers, 2006 to 2026). A malignant, usually aggressive tumor composed of atypical, neoplastic melanocytes. "The association of TLR4 polymorphism (rs4968790) with clinical and pathological features in melanoma patients was assessed." (PMID 38606218, 2024). "TLR4 has shown to be overexpressed in melanoma tumors and associate to decreased survival, which links hyaluronan and TLR4 in melanomagenesis." (PMID 35127523, 2021). "We can collect additional patient melanoma samples to study the roles of gene polymorphisms of TLR4, MYD88, TRIF, and STAT3 in melanomagenesis in the future." (PMID 32312954, 2020). "Further, we found that the effects mediated by activating TLR4 are weakened by suppressing STAT3 function with a dominant negative STAT3 variant in melanoma." (PMID 32312954, 2020). "We found that both LPS and MPLAs significantly increased cell proliferation and invasion in B16NC cells but not in B16STAT3β cells, suggesting a critical role of STAT3 activation in TLR4 signaling-caused melanoma progression." (PMID 32312954, 2020). "In human melanoma it has been reported that high TLR4 expression is associated with a shortened relapse-free survival." (PMID 25973756, 2015). "Cationic liposomes have been found to potentiate anti-tumor immune responses induced by poly(I:C) in murine melanoma models, and to engage TLR4 on tumor associated macrophages that also resulted in anti-tumor immune response." (PMID 25411122, 2014). "The haplotype A-T-A-G-A-G-G-C of the TLR4 gene locus associated with a decreased risk for melanoma compared to the most frequent haplotype A-T-C-A-A-G-G-T (OR 0.72, 95%CI 0.57–0.91)." (PMID 21931695, 2011). "The variant allele for TLR2-rs3804099 was associated with an increased risk (OR = 1.15, 95% CI 0.99–1.34, p = 0.07) and for TLR4-rs2149356 with a decreased risk (OR = 0.85, 95% CI 0.73–1.00, p = 0.06) of melanoma." (PMID 21931695, 2011). "In conclusion, on the role of variants in eight TLR genes in malignant melanoma show an association of one variant in the TLR4 gene with the disease survival." (PMID 21931695, 2011). "Our data showed that melanoma patients carrying the variant allele for the rs4986790 polymorphism in the TLR4 gene were associated with a prolonged OS." (PMID 21931695, 2011). "However, apart from its effects on FGF signaling, autocrine PTX3 in melanoma has been linked to the TLR4/NF-κB signaling pathway, where it exerts opposing effects." (PMID 41479916, 2025). "This dual role may underlie the association we observe between TLR4 genetic variation and immune-related adverse events (irAEs) in patients receiving immunotherapy for melanoma." (PMID 40721801, 2025). "TLR-4 was associated with the up-regulation of pro-inflammatory cytokines in melanoma cells." (PMID 36834531, 2023). "Moreover, the interaction of TLR2, TLR3 and TLR4 with their ligands on human melanoma cells was associated with increased cell migration and tumour metastasis." (PMID 33336901, 2021). "Additionally, an increased TLR4 expression associated with a shorter relapse-free survival time in cutaneous malignant melanomas, a poorer differentiation state in lung cancer, and a larger tumor size in murine experimental melanoma lung metastases." (PMID 32424768, 2020). "Toll-like receptor 4 (TLR4) has been linked to melanoma growth, angiogenesis and metastasis." (PMID 32312954, 2020). "Whether TLR4 signaling activates STAT3 through the MYD88 and TRIF pathways in the two cancer types, as we observed in melanoma, and whether TLR4/STAT3 signaling plays a pathogenic role in the two cancers warrant further investigations." (PMID 32312954, 2020). "In addition, injection ofpreventive DC-based vaccines transfected with mRNA encoding polypeptideβ2m-tumor peptide-TLR4 orprepared using living B16 melanoma cells as a source of TAA fully protected animals against thedevelopment of B16 melanoma." (PMID 29104773, 2017).